FOSL2 (FOS like 2, AP-1 transcription factor subunit)
Diseases named in the same sentence as FOSL2 in open-access papers (continued):
Sharing a sentence is not in itself a finding about the gene and the disease.
tumor (continued). "Caveolin 1 (CAV1) and FOS-like antigen 2 (FOSL2) expressions have been shown to be elevated in many human cancer cell lines and numerous human tumor specimens, thereby indicating that CAV1 and FOSL2 play important roles in the promotion of mammary tumorigenesis." (PMID 23023193, 2012). "Growing evidence has shown that miR-133a is downregulated and plays tumor suppressor roles in cancer and that it can inhibit proliferation, migration, and invasion of HCC cells by targeting several genes such as IGF-1R, FSCN1, and FOSL2 through the TGF-β/Smad3 signaling pathway." (PMID 35432524, 2022). "However, the role of tumor stroma-derived FOSL2 signaling in tumors has not been clarified." (PMID 33754039, 2021). "Moreover, many genes (PTN, SIAH2, FAM111B, TMEM43, FOSL2, TRIB1 and SPATA1) were hypomethylated regardless of tumor grade." (PMID 36850002, 2023).
cancer (51 papers, 2012 to 2026). A tumor composed of atypical neoplastic, often pleomorphic cells that invade other tissues. "As a member of the AP-1 TF family, FOSL2 has been implicated in various cancers, emphasizing its role in tumorigenesis and disease progression." (PMID 39964764, 2025). "FOSL2 is a member of the AP-1 transcription factor family and is associated with the development of a variety of cancers." (PMID 33712565, 2021). "Meanwhile, FOSL2 gene expression has been linked to fat metabolism, cancer, and bone diseases in human and animals." (PMID 28050569, 2016). "We found that FOSL2 collaborates with KLF6 to regulate the expression of SEMA3C, a protein that has been implicated in cancer progression." (PMID 40082673, 2025). "Specifically, the elucidated interplay between KLF6, TAF6L and FOSL2, along with their regulatory influences on SEMA3C and the Wnt-β-catenin pathway, enhancing our understanding of the complex networks underlying cancer drug resistance." (PMID 40082673, 2025). "We further explored the current knowledge and suggest a common aggressive cancer mechanism via the FOSL2/AP-1-mediated enhancer network." (PMID 40781158, 2025). "As examples, we experimentally validated three rare variants in cancer-associated genes (MFN2, FOSL2, and IRAK1), confirming their functional roles in regulating mRNA stability and cell proliferation." (PMID 38637555, 2024). "Through prime editing, we characterized three variants in cancer-relevant genes (MFN2, FOSL2, and IRAK1), demonstrating their cancer-driving potential." (PMID 38637555, 2024). "Taken together, our data uncover the implications of a SOX2-regulated gene expression network controlling cancer aggressiveness via FOSL2 by activating and sustaining pro-inflammatory TME leading to DNA damage and genomic instability." (PMID 36932385, 2023). "Many of these genes, such as VIM, FOSL2, PTN, GPR3, SIAH2, UPP1, S100A2 are associated with cell migration and epithelial-mesenchymal transition (EMT) in several cancers." (PMID 36850002, 2023). "To further investigate the relevance of the SOX2/FOSL2 axis in disease aggressiveness, we extracted the SOX2 segment mean from all cancer entities and determined a threshold associated with better overall survival." (PMID 36932385, 2023). "Our work therefor provides the mechanistic basis of these observations as well as a cancer overarching implication of SOX2/FOSL2 in driving cancer aggressiveness." (PMID 36932385, 2023). "FOSL2, which showed higher RNA expression in cancer cells, was also significantly correlated with the poorer overall survival of the patients." (PMID 35165277, 2022). "For example, higher levels of EGFLAM and FOSL2 have been reported to correlate with poor prognosis and therefore considered as prognostic biomarkers and therapeutic targets in some cancers." (PMID 35641855, 2022). "We additionally found TGF-β to upregulate FOSL2 levels (relative to Th0), which complies with previous findings in cancer cells." (PMID 35511484, 2022). "Meaningfully, FOSL2 has been identified as the promoter of EMT on TGF-β/Smad3 signaling pathway in advanced cancers." (PMID 32552766, 2020). "Taken together, we have shown that the FOXA1/JUND /FOSL2-TXNDC9-MYC regulatory network promoted cancer progression of HCC." (PMID 30382079, 2018). "Consistently, a recent work on a small cohort of patients reported that germinal mutations in FOSL2 have been associated with neurodevelopmental delay and no increased risk of cancer was observed." (PMID 38104183, 2024). "To establish the involvement of FOSL2 in disease aggressiveness, we performed differentially gene expression analysis comparing poor and better outcome entities as well as FOSL2high and FOSL2low tumors using data from all 27 cancer entities." (PMID 36932385, 2023). "A growing body of evidence suggests a cardinal role for FOSL2 in cancer, especially metastasis." (PMID 36139487, 2022).
cancer (continued). "FOSL2 acts as an important part of cancer, photoperiodic regulation and T cell differentiation." (PMID 33739370, 2021). "Aberrantly increased expression of FOSL2 has been documented in many cancer types, including CRC." (PMID 34782005, 2021). "FOSL2 exerts a specific function in bone development and appears to have selective physiological and pathological roles in diverse processes, including photoperiodic regulation, cancer, and fibrosis." (PMID 25375657, 2014). "Therefore, the observation suggests that therapy interfering with the lncRNA UCA1/miR-143/FOSL2 axis could offer a new line of treatment for cisplatin-resistant cancers." (PMID 36139487, 2022). "The upregulation of mRNA expression of several oncogenes, including FOSL2, TUFT1, HMGA1, and HDGF, most often leads to the acquisition of cisplatin resistance, while increasing the proliferation of cancer cells and reducing their apoptosis." (PMID 36139487, 2022). "Increasing studies have demonstrated that HNF4A, FOSL2, and GATA4 showed aberrant expression in various malignant tumors, playing a role in promoting or inhibiting malignancies, and our study results were consistent with these studies." (PMID 33588380, 2021). "Notably, hsa‐miR‐423‐3p and hsa‐miR‐4286 were upregulated and are known to target cancer‐related genes such as JUNB and members of the AP‐1 family (FOS, FOSL2, ATF‐6B)." (PMID 39575761, 2025). "Moreover, we discovered that FOSL2 upregulates SEMA3C and c-Myc in 5-FU-resistant HCT15 cells through the canonical Wnt–β-catenin signaling pathway, a critical pathway known to drive cancer growth and survival." (PMID 40082673, 2025). "Hence, exploring the functions and mechanisms of FOSL2 in PDAC and other cancers holds significant value." (PMID 37380804, 2023). "In conclusion, we found that the cancer-related CNVs of CEP63, FOSL2 and PAQR6 were competent in evaluating recurrence or progression risk for BC patients and may be used for the risk group stratifications in the future." (PMID 34041036, 2021). "Although there are currently no inhibitors targeting FOSL2 for cancer treatment, targeting downstream effectors of FOSL2 may provide an alternative strategy." (PMID 37380804, 2023).
infection (10 papers, 2010 to 2026). The state of being infected such as from the introduction of a foreign agent such as serum, vaccine, antigenic substance or organism. "Considering the significant changes and high expression level of FOSL2 in HepLPC-P10, FOSL2 was selected to perform interference experiments with short hairpin RNA-mediated FOSL2 (shFOSL2) knockdown via lentiviral infection to verify its effect on the aging of HepLPCs." (PMID 37173651, 2023). "The level of the epigenetic marker at the position of genes WNT10A, JUNB, FOSL2, TNFAIP3, KLF4 and EDN1 was increased, and decreased at the position of genes MYCN and PCSK9, as was demonstrated by using the in vitro HCV-infection systems." (PMID 31216276, 2019). "Under Ad-vaspin infection, we observed increases in the levels of c-Fos and c-Jun but no changes in Fosl1, Fosl2, FosB, JunB or JunD." (PMID 40025171, 2025). "Notably, 12 of these TFs exhibited distinct phosphorylation patterns upon infection, including MED14, SIN3A, BCL6, cJUN, NFATC1, STAT3, RUNX3, GTF2F1, MED1, JUNB, TLE3, and FOSL2." (PMID 40368139, 2025).
inflammation (2 papers, 2022 to 2023). Aberrant reaction of the microcirculation characterized by movement of fluid and leukocytes from the blood into extravascular tissues. "These mice overexpress the AP-1 transcription factor Fra2, encoded by Fosl2, leading to the development of spontaneous systemic inflammation and fibrosis, primarily in the lung and skin." (PMID 37700377, 2023).
immune disorders (1 paper, 2024). "While some of these regulatory factors (e.g., NFKB, STAT, and IFN) have been reported as shared TFs enriched in inflammatory fibroblasts across a diverse group of immune disorders, others displayed distinctive TFs (e.g., FOSL2, JUN, and ELK4) unique to inflammatory keratocytes." (PMID 39677756, 2024).
FOSL2 also shares sentences with these, for which no sentence is quoted: vasculopathy (7 papers); asthma (5); liver cancer (4); scleroderma (4); fibrosis (3); idiopathic pulmonary fibrosis (3); pancreatic ductal adenocarcinoma (3); squamous cell carcinoma (3); allergic asthma (2); eosinophilia (2); gastric cancer (2); interstitial lung disease (2); iron deficiency (2); lung disease (2); mesothelioma (2); metabolic disease (2); osteosclerosis (2); pilocytic astrocytoma (2); prostate carcinoma (2); tongue cancer (2); tongue tumor (2); triple-negative breast carcinoma (2); acute myeloid leukemia (1); acute myocardial infarction (1); adenocarcinoma (1); allergic disease (1); allergic rhinitis (1); alveolitis (1); anaphylaxis (1); atherosclerosis (1).
A further 48 diseases each share a sentence with FOSL2 in 1 paper.